ATG4B (autophagy related 4B cysteine peptidase)
Diseases named in the same sentence as ATG4B in open-access papers (continued):
Sharing a sentence is not in itself a finding about the gene and the disease.
cancer (continued). "Nevertheless, autophagy inhibition not only impedes cancer cell viability, but also play dual roles in immune cells by either enhancing or disrupting their cytotoxic activity, which requires further determination for the justification of ATG4B inhibitors in cancer treatment." (PMID 37038218, 2023). "This promoted us to examine whether ATG4B exerted critical functions in other cancer types." (PMID 35184132, 2022). "Additionally, ATG4B is involved in development of chemoresistance in numerous cancer types." (PMID 35193115, 2022). "In addition, the activity and function of ATG4B were regulated in several ways, and the development of its inhibitors may also become a promising direction for cancer therapy." (PMID 36539845, 2022). "Therefore, we look forward to characterizing the link (if any) between EVA1A and Atg4B, and whether flubendazole could regulate both of these factors to further affect autophagy in cancer." (PMID 32724459, 2020). "Therefore, ATG4B may be a potential drug target for cancer and inhibition of ATG4B activity may serve as a new mean for cancer therapy." (PMID 32532053, 2020). "Small molecules that inhibit autophagy by targeting autophagy-related 4B cysteine peptidase (ATG4B), UNC-51-like autophagy-activating enzymes (ULK1), and LC3-associated phagocytosis (LAP) have yield promising results in in vitro studies using cultured cancer cells." (PMID 30744190, 2019). "Thus, it seems that the application of ATG4B inhibitors to modulate autophagy and cancer cell growth may have to be context-dependent." (PMID 31083460, 2019). "Conversely, numerous studies have demonstrated that elevated expression levels of ATG4B, ATG5, and Beclin‐1 in tumor tissues correlate with poor pathological outcomes in cancer patients." (PMID 40883962, 2025). "ATG4 (ATG4A, ATG4B, ATG4C and ATG4D), a cysteine protease family, plays a crucial role in autophagy signaling and correlated with cancer progression in different types of cancers." (PMID 37038218, 2023). "ATG4B, the core autophagy protein in ATG8/LC3 system, was found to be up-regulated in cancer tissue in our study." (PMID 33604190, 2021). "Based on the screening, chemicals with a 2-phenylbenzofuran structure exhibited a strong inhibition effect on ATG4B and cancer cell viability, suggesting the structure with a 2-phenyl benzofuran might be a good pharmacophore to develop ATG4B inhibitors for cancer therapy." (PMID 32532053, 2020). "Specifically, ATG4B was highly upregulated at both the transcript and protein levels, indicating that ATG4B may be a potential biomarker and target for CML cancer stem cells." (PMID 32195258, 2020). "Apart from ATG4B, other mammalian ATG4 homologues may also be potential therapeutic targets for cancer, particularly ATG4D, which plays a notable role in apoptosis." (PMID 31083460, 2019). "Within the EBV-positive subgroup, higher expression of ATG4B and ATG4D was more prevalent in regional carcinomas compared to localized or distant carcinomas (P = 0.031 for ATG4B; P = 0.048 for ATG4D), though this trend was not significant in the overall cohort (P = 0.061 for both ATG4B and ATG4D)." (PMID 40630202, 2025). "However, there are no reports in the literature on the prognostic value of ATG4B, or any of the other ATG4 family members, in cancers." (PMID 28696368, 2017). "Moreover, ATG4-family proteins have four homologues and thus the reported ATG4B inhibitors could also target other ATG4s, it is necessary to understand whether specific ATG4B inhibitors or non-selective ATG4 inhibitors have better anti-cancer effects." (PMID 31083460, 2019).
tumor (46 papers, 2016 to 2026). "Overexpression of ATG4B has been linked to tumor progression and resistance to chemotherapy or radiation therapy." (PMID 40883962, 2025). "Increased expression levels of ATG4B are associated with both tumor progression and therapy resistance." (PMID 34868951, 2021). "We found that both ATG4B and phospho-Ser383/392-ATG4B were elevated in tumor tissues of OSCC and associated with poor prognosis in certain stages of OSCC." (PMID 31771238, 2019). "Given the critical role of autophagic regulation in controlling tumor immune evasion and cell death, the present study investigates the effects of BCc1 on key autophagy-associated genes ATG-4B, ATG-7, Beclin-1 and the mTOR signaling pathway using a BALB/c mouse model of BC." (PMID 41550506, 2026). "BCc1 exhibits a dual regulatory effect—upregulating tumor-suppressive Beclin-1 while downregulating pro-survival ATG-4B, ATG-7, and mTOR—in a manner dependent on dose and administration route." (PMID 41550506, 2026). "There was a significant positive correlation between ATG4B expression and tumor size, tumor stage, and histological response to neoadjuvant chemotherapy, with p values of 0.013, 0.008, and 0.022, respectively." (PMID 40279002, 2025). "Targeting ATG4B has been reported to inhibit tumor proliferation and metastasis significantly in vitro." (PMID 38803355, 2024). "Limited cohort study (n = 20) shows that ATG4B protein level is elevated in tumor parts of CRC patients." (PMID 37038218, 2023). "Our present study indicated that both ATG4B and its active form pS383/392-ATG4B were elevated in tumor cells of CRC patients compared to adjacent normal cells." (PMID 37038218, 2023). "Other autophagy modulators, such as VPS34, ULK1, and ATG4B inhibitors have been confirmed to exert tumor suppressor effect in clinical mouse models." (PMID 36900050, 2023). "ATG4B gene expression was elevated in tumor tissues of CRC patients compared to that in adjacent normal tissues and high level of ATG4B expression was associated with poor survival." (PMID 37038218, 2023). "Paired t test performed on the results of immunoblotting analysis of paired gastric normal and tumor tissues revealed that ATG4B was overexpressed in over 50% of the tumors." (PMID 35184132, 2022). "Among them, ATG4B was validated to be highly expressed in CRC tumor tissues, and its knockdown resulted in blocking cell cycle progression and inhibition in CRC cells, typically HCT116 cell line." (PMID 36539845, 2022). "In this study, we found that high ATG4B expression correlated with poor survival of patients with GCa and was essential for tumor growth." (PMID 35184132, 2022). "Ultimately through cell culture and mouse xenograft tumor models, we established the impact of Ebselen on autophagy and tumor suppression via ATG4B inhibition other than apoptosis." (PMID 36539845, 2022). "At the present, the mechanism that miR-34a/ATG4B regulated autophagy had already been described in tumor cells and epithelial cells after kidney injury." (PMID 36345369, 2022). "Through mRNA and protein analysis of GCa clinical tumor samples, we found that autophagy-related gene 4B (ATG4B) was overexpressed in GCa tumors and that its high expression was associated with patients’ poor prognosis." (PMID 35184132, 2022). "Am-F4a, as a novel ATG4B inhibitor, potently inhibited GCa tumor growth and metastasis in vitro and in vivo." (PMID 35184132, 2022). "In another study, small molecules with a benzotropolone backbone structure will be an effective approach to enhance the sensitivity to chemotherapy and attenuate tumor growth by the impairment of autophagy through targeting ATG4B." (PMID 36034776, 2022). "Am-F4a significantly inhibited GCa cell survival and tumor growth via suppressing ATG4B activity and downstream processes." (PMID 35184132, 2022).
tumor (continued). "The tumor therapeutic potential of Ebselen via ATG4B was also further evaluated by immunohistochemical staining for Ki67, an indicator of tumor malignant proliferation." (PMID 36539845, 2022). "Recent studies have shown that ATG4B promotes the proliferation and progression of various tumor cells, and enhances the drug resistance of HCC cells through inducing protective autophagy." (PMID 34409031, 2021). "In this study, we provide a new therapeutic strategy and aim to identify a dual functional molecule that simultaneously targets ATG4B and lysosome to inhibit autophagy, potentially serving as promising anti-tumor agents." (PMID 32532053, 2020). "In summary, we have generated a novel dual-effective autophagy inhibitor 163N that targets both ATG4B and lysosome to effectively inhibit tumor growth in vitro and in vivo." (PMID 32532053, 2020). "Recently, a very elegant study was performed to assess the consequence of ATG4B inhibition in already-formed tumours, using a genetically engineered mouse model expressing the catalytic inactive version of ATG4B." (PMID 31878323, 2019). "Overexpression of catalytic mutant ATG4BC74A arrests cell growth of glioma and hepatocellular carcinoma cells, indicating that proteolysis of ATG4B is essential for tumor growth." (PMID 31771238, 2019). "Here, we reported the following findings: First, the protein levels of ATG4B and phospho-Ser383/392-ATG4B were significantly elevated in tumor tissues compared with adjacent normal tissues in both BMSCC and TSCC." (PMID 31771238, 2019). "Notably, unlike Beclin-1, which is contextually activated to facilitate tumor-suppressive autophagy, ATG-4B suppression by BCc1 represents a selective inhibition of pro-survival autophagic flux." (PMID 41550506, 2026). "ATG-4B, a cysteine protease critical for autophagy, exhibits complex and context-dependent roles in oncogenesis, functioning either as a tumor suppressor or as a facilitator of tumor progression depending on cellular and microenvironmental conditions." (PMID 41550506, 2026). "Collectively, these findings suggest that BCc1 may act as a dual-function nanomedicine, capable of modulating tumor-suppressive autophagy (via Beclin-1) while inhibiting pro-survival autophagy (via ATG-4B)." (PMID 41550506, 2026). "Although several studies have demonstrated the critical role of ATG4B in tumor cells and the utility of ATG4B inhibitors in tumor inhibition, the underlying mechanism by which ATG4B blockade hampers tumor cell growth has not been fully studied." (PMID 41275290, 2025). "Notably, ATG4B is highly expressed in tumor tissues but shows minimal expression in adjacent normal tissues of colorectal and oral cancer patients." (PMID 40883962, 2025). "Knockdown of ATG4B significantly inhibited GCa cell survival and tumor growth." (PMID 35184132, 2022). "In this regard, ATG4B(C74A) has been demonstrated to induce tumor regression in PDAC bearing mice." (PMID 35372352, 2022). "Notably, knockdown of ATG4B potently suppressed tumorigenesis and tumor growth in mice GCa xenograft models." (PMID 35184132, 2022). "Moreover, Am-F4a or ATG4B knockdown significantly suppressed tumor growth as well as GCa cell migration and invasion." (PMID 35184132, 2022). "ATG4B is overexpressed in tumor cells of colorectal patients." (PMID 35184132, 2022). "In a study using a PDAC mouse model expressing a tetracycline-inducible dominant-negative ATG4B protein which can reversibly and acutely inhibit autophagy in fully formed tumors, the inhibition of autophagy was shown to suppress tumor growth via intrinsic as well as extrinsic factors in tumor cells." (PMID 36408139, 2022). "Therefore, ATG4B inhibition blocks GCa tumor growth and metastasis, possibly through inhibiting multiple pathways, including autophagy." (PMID 35184132, 2022). "ATG4B has a potential role in tumor progression, but the effect of ATG4B phosphorylation remains unclear." (PMID 35456009, 2022).
tumor (continued). "However, the overall impact of ATG4B inhibition on tumor growth is unlikely limited to suppress autophagy." (PMID 35184132, 2022). "In addition, as elevated CRNDE expression is typically found in a variety of malignancies, more studies are required to explore if the CRNDE-triggered upregulation of ATG4B exists functionally in other correlated neoplastic diseases." (PMID 34409031, 2021). "Given that ATG4B inhibitors with diverse structures are able to inhibit tumor growth, it cannot be excluded that ATG4B inhibiting compounds may also affect other targets than ATG4B." (PMID 34868951, 2021). "Tioconazole was also identified to be a potent ATG4B inhibitor, which could diminish autophagic flux and enhance the anti-tumor effect of chemotherapeutic drugs." (PMID 32532053, 2020). "Thereafter, 163N bearing the structure of both 2phenylbenzofuran for ATG4B and 6-methylpyrimidine-2,4-diamine for lysosome might be a potential dual functional tumor inhibitor." (PMID 32532053, 2020). "Pearson’s correlation analysis results indicated that ATG4B expression had a moderate positive correlation with phospho-Ser383/392-ATG4B expression in the tumor tissues of BMSCC, while it showed a low positive correlation with phospho-Ser383/392-ATG4B expression in TSCC." (PMID 31771238, 2019). "We further investigated whether the protein levels of ATG4B are correlated with those of phospho-Ser383/392-ATG4B in tumor tissues of OSCC." (PMID 31771238, 2019). "With a tissue microarray comprising specimens from 428 OSCC patients, including 179 BMSCC and 249 TSCC patients, we found that the protein levels of ATG4B and phospho-Ser383/392-ATG4B were elevated in the tumor tissues of BMSCC and TSCC compared with those in adjacent normal tissues." (PMID 31771238, 2019). "Another important aspect is how ATG4B inhibition may affect host cell autophagy that has been shown to fuel tumour growth through various mechanisms, such as arginine secretion." (PMID 31878323, 2019). "Age was positively correlated with the fall in expression levels between healthy and tumor cells of the three following genes: ATG4B (Spearman’s correlation coefficient R = 0.352; p = 0.002), and MAP1LC3A (Spearman’s correlation coefficient R = 0.279; p = 0.017)." (PMID 30374741, 2018). "The findings demonstrate a robust downregulation of ATG-4B expression across various treatment conditions, with BCc1 and cyclophosphamide showing particularly strong effects, further implicating autophagy-related genes as potential therapeutic targets in the tumor microenvironment." (PMID 41550506, 2026). "Therefore, ATG4B is essential for GCa cell survival and tumor growth." (PMID 35184132, 2022). "Furthermore, NSC185058 as an ATG4B antagonist can suppress tumor growth by autophagy inhibition." (PMID 36034776, 2022). "Moreover, ATG4B inhibitors with diverse structures were able to inhibit tumor growth in vivo, implying that these compounds may also affect targets other than ATG4B in cells." (PMID 31083460, 2019). "Our study sought to delineate the molecular underpinnings of BCc1's anti-tumor effects in a BALB/c murine model of BC, focusing on key autophagy regulators (Beclin-1, ATG-4B, ATG-7) and the mTOR signaling axis." (PMID 41550506, 2026). "Second, the apparent parallel modulation of ATG-4B by both BCc1 and cyclophosphamide suggests a potential pharmacodynamic convergence that could be strategically leveraged in combination regimens to achieve synergistic targeting of autophagy-dependent tumor resilience." (PMID 41550506, 2026). "The increased autophagy activity induced by highly expressed autophagy-related genes including ATG4B decreases the expression of SESN3, a novel tumor-suppressor in T-ALL through autophagy-mediated protein degradation and EGR1-regulated transcription." (PMID 41275290, 2025).
tumor (continued). "Another potential regulator of the retrieval step is the tumor suppressor, miR-34a, which has recently been identified as an inhibitor of the autophagic flux and a direct regulator of ATG9A and ATG4B in mammalian cells." (PMID 36000264, 2022). "To date, some published inhibitors of ATG4B had been tested in xenograft models of CRC cell lines and exhibited certainly tumor growth suppression." (PMID 36539845, 2022). "An additional HER2 positive cell line xenograft tumor model, JIMT1, was treated with trastuzumab and showed similar effects on ATG4B levels." (PMID 27556700, 2016). "Notably, this study represents the first global exploration of BCc1 nanomedicine's potential to induce autophagy, a process mediated by autophagy-related genes (Beclin-1, ATG-4B, ATG-7, and mTOR), while evaluating tumor cell death." (PMID 41550506, 2026). "Additionally, ATG4B closely interacts with SLC2A1, promoting the Warburg effect in tumor and increasing L-lactate production and glucose uptake." (PMID 41019083, 2025). "Interestingly, the levels of ATG4B, LC3II/LC3I, and SQSTM1/P62 were all up-regulated in mouse tumor tissues that overexpressed GABARAPL1, suggesting an up-regulation of autophagy in the tumor." (PMID 38234672, 2024). "ATG4B gene expression was significantly higher in tumor tissues of CRC patients compared with those in adjacent normal tissues." (PMID 37038218, 2023). "A large body of evidence suggests that inhibition of the activity of other ATG4 family members, including ATG4A, ATG4B and ATG4D, could suppress tumor progression and enhance chemosensitivity or the efficacy of radiotherapy." (PMID 31291988, 2019). "From the results, we noticed that tumor cells highly expressed AUP1 significantly correlated with proliferation marker (MCM2, MCM6), PI3K-AKT-MTOR pathway (Akt1, TSC1, mTOR, Foxo1), and autophagy signaling (Atg3, Atg4B, Atg4D, Atg7, Atg9A, Atg16L1) in IDH wildtype tumor cells." (PMID 37029364, 2023). "FMK-9a was shown to be the most potent ATG4B inhibitors so far, but it could neither inhibit autophagy nor reduce tumor cell viability." (PMID 32532053, 2020). "Moreover, inhibition of autophagy by 163N had a stronger inhibition effect on tumor cell migration than just genetic deletion of ATG4B, indicating that single ATG4B knockout is not enough to inhibit tumor cell migration." (PMID 32532053, 2020). "Thus, we could not deny that Ebselen played some role in suppressing the tumor model malignancy by inhibiting autophagy via ATG4B." (PMID 36539845, 2022). "Moreover, we could also find that inhibition of autophagy by 163N exhibited a much stronger inhibition effect on tumor cell viability than the genetic deletion of ATG4B, implying that only ATG4B inhibition is likely not sufficient to suppress tumor growth." (PMID 32532053, 2020). "Thus, the protease activity of ATG4B in formalin-fixed tissues might not completely reflect the autophagic flux in tumor tissues." (PMID 31771238, 2019).
infection (9 papers, 2017 to 2025). The state of being infected such as from the introduction of a foreign agent such as serum, vaccine, antigenic substance or organism. "tomato (Pto) DC3000 infection, effector HrpZ1 oligomerization targets the ATG4b-mediated cleavage of ATG8 to enhance autophagy, while HopF3 targets ATG8 to suppress autophagy." (PMID 35308338, 2022). "However, our findings, along with other reports, demonstrate that mutations or absence of Atg7, Atg4b, LC3b, or Atg16L1 can trigger a protective response against the infection." (PMID 39971913, 2025). "In addition, other autophagy-related proteins—Atg2b, Atg4b, and Dynll1—also showed similar expression patterns, suggesting that membrane recruitment of proteins to the autophagosome may be important for the DC response to infection." (PMID 32041786, 2020). "The mRNA expression of other ATG genes in WT, such as the mRNA expression of ATG4a and ATG4b decreased and then rise; the mRNA expression of ATG5 and ATG12a decreased with the infection time of AvrRpt2 (data not shown); these are very interesting." (PMID 32708160, 2020). "The requirement of autophagy-initiation proteins ULK1, Beclin 1, and ATG14L and PI3-kinase activity but not elongation proteins ATG5, ATG16L1, ATG4B, ATG7, and LC3B suggested Brucella selectively co-opts autophagy-initiation complexes to subvert host clearance and promote infection." (PMID 38376367, 2024).
Bacterial Infection (3 papers, 2012 to 2020). "RNF5 controls the membrane fraction of ATG4B and limits LC3 (ATG8) processing, aberrant of which may limit basal levels of autophagy and influence susceptibility to bacterial infection." (PMID 23527081, 2013).